EPHB4 (EPH receptor B4)
Diseases named in the same sentence as EPHB4 in open-access papers (continued):
Sharing a sentence is not in itself a finding about the gene and the disease.
glioma (continued). "Using an ecotropic transfection system, empty vector (pLXSN) or EphB4 (EphB4OE) overexpressing Phoenix-ECO cells were coimplanted with SF126 glioma cells subcutaneously (dorsal skinfold chamber, DSC) and orthotopically (cranial window, CW)." (PMID 29987450, 2018). "In agreement with this, stimulation of ephrinB2 reverse signalling with its cognate receptor EphB4 decreased invasion in human glioma cell lines that express ephrinB2." (PMID 27470974, 2016). "Upregulation of ephrin-B2/EphB4 has been observed in many tumors, including ovary, colon, breast, and glioma, with a strong correlation with poor prognosis." (PMID 22292016, 2012). "Beyond its role in cell motility, EphB4 also contributes to glioma vascular remodeling." (PMID 41200151, 2025). "Towards this direction, EPHB4/ephrin-B2 signaling is explored as an antiangiogenic target, with anti-EPHB4 monoclonal antibodies successfully blocking EPHB4 signaling, while inhibition of EPHA2 and EPHB1-3 forward signaling in gliomas is associated with a dose-dependent reduction in cell invasion." (PMID 38612645, 2024). "Regarding specific angiogenetic effects of EphB4 and subsequent antiangiogenic resistance, endothelial overexpression of EphB4 during glioma growth in vivo, effectuates significantly enlarged tumor vessels, which seemingly organized themselves to a more structured network." (PMID 35163601, 2022). "EphB4/ephrin-B2 is highly expressed in many malignant tumor cells, including glioma cells." (PMID 35448036, 2022). "Interestingly sunitinib-resistant and temozolomide-resistant glioma vessels demonstrate the same vascular phenotype as EphB4 overexpressing glioma vessels." (PMID 29987450, 2018). "Further studies will have to focus on EphB4 mediated effects using different glioma cell lines and loss of function approaches to characterize EphB4 signaling depending on the oncobiological context to support clinical translation of EphB4 as a potential target in glioma resistance." (PMID 29987450, 2018). "The increased propensity of ephrinB2 KO gliomas for diffuse invasion in a parenchymal environment was corroborated by co-cultivation with normal brain astrocytes expressing the ephrinB2 receptors EphB2 and EphB4." (PMID 27470974, 2016). "The RMPAhigh gliomas were enriched in immature vessel cells and tumor associated macrophages, and both cell types expressed high levels of pro-angiogenic RTKs including MET, VEGFR1, KDR, EPHB4 and NRP1." (PMID 27385209, 2016). "Because EphB4 is involved in neural development, it may be possible that it also has an effect on the regulation of glioma CSCs." (PMID 25787115, 2015). "Therefore, EphB4 signaling retains glioma cells in the central portion of the tumor via a positive feedback loop, and liberation of the cells from EphB4 signaling may be responsible for their invasion into the brain." (PMID 35448036, 2022). "Therefore, it may be speculated that different expression profiles of ephrinB2 and EphB4 and the associated equilibrium between receptor and ligand account for the reported different effects of EphB4 overexpression in glioma biology." (PMID 29987450, 2018). "A poor prognosis has been documented for pediatric patients with gliomas overexpressing EPHA7, alveolar-type rhabdomyosarcomas overexpressing EPHB4, and osteosarcomas presenting ephrin-A4 cytoplasmic expression." (PMID 38612645, 2024). "Consistent with our results, high expression of HDAC1, CASP3, REST, GNAI3, FZD1, EPHB4 was found to correlate with poor prognosis of glioma, and inhibitors of HDAC1 inhibited the EMT process in glioma cells thereby affecting cell migration and invasion." (PMID 38629068, 2024). "Histological analysis of glioma tissue shows increased, global expression of EFNB2 and some EPHB4 expression in tumor cells." (PMID 35629359, 2022).
glioma (continued). "We demonstrate that endothelial EphB4 overexpression leads to maintenance of pericyte–endothelial interactions despite effective anti-VEGF and anti-PDGF treatment leading to resistant glioma vasculature in a subcutaneous SF126 glioma model." (PMID 29987450, 2018). "In the RMPAlow gliomas, a different set of RTK signaling-related genes including MET (8.9%), EPHA1 (8.9%), EPHB6 (8.9%), EPHB4 (8.3%), BRAF (8.9%), FGF6 (11.9%), FGF23 (11.9%), NTF3 (11.9%), and ANGPT1 (9.5%) were amplified." (PMID 27385209, 2016). "In these RMPAhigh gliomas, angiogenic related RTKs including MET, VEGFR1, KDR, EPHB4, NRP1 were frequently and concomitantly expressed in CD45+ immune cells and CD105+ endothelial cells." (PMID 27385209, 2016). "TAMs are enriched in the RMPAhigh gliomas and they show high surface expression of MET, VEGFR1, KDR, EPHB4 and NRP1." (PMID 27385209, 2016). "Though gliomas with RMPAlow signature contained fewer CD45+ cells and CD105+ cells, CD45+ cells in these gliomas also expressed VEGFR1, KDR, EPHB4 and PLXNB2." (PMID 27385209, 2016). "In summary, it is not possible to dismiss the antiangiogenic effects of EphB4 and ephrinB2 in terms of mediating resistance towards antiangiogenic treatment in glioma." (PMID 35163601, 2022). "Therefore, it was the aim of the current study to investigate the influence of EphB4 overexpression on microcirculation and vascular resistance using SF126 glioma cells in different experimental approaches." (PMID 29987450, 2018). "EphB4 overexpression leads to vascular resistance by altering vascular morphogenesis, pericyte coverage, and cellular proliferation/apoptosis in experimental SF126 glioma models." (PMID 29987450, 2018). "Furthermore, circRNA EPHB4 modulates stem properties and proliferation of gliomas via sponging miR-637 and upregulating SOX10, indicating that the RTK pathway may be involved in glioma development and progression mediated by circRNA-miRNA interactions." (PMID 38200584, 2024).
melanoma (16 papers, 2005 to 2025). A malignant, usually aggressive tumor composed of atypical, neoplastic melanocytes. "With regard to cancer-related signaling cascades, we observed an altered phosphorylation pattern for 31 phosphorylation variants as a consequence of EphB4 overexpression in A375 melanoma cells." (PMID 33153234, 2020). "Experimental evidence has associated receptor tyrosine kinase EphB4 with tumor angiogenesis also in malignant melanoma." (PMID 29462967, 2018). "In A375 melanoma xenografts, EPHB4 overexpression promoted tumor growth but prevented vascularization." (PMID 38426087, 2024). "EPHB4 likely imparts similar effects in the melanoma immune environment, in accordance with the effects of hypoxia generation." (PMID 38426087, 2024). "In melanoma metastasis, EphB4 on tumor cells is critically involved in endothelial cell–tumor cell repulsion and downregulation or loss of ephrinB2 on endothelial cells increased bone metastatic burden in vivo." (PMID 35163601, 2022). "EphB4 stimulation during tumor cell seeding led to an increase in spinal metastatic loci and number of disseminated melanoma cells, as well as earlier locomotion deficits in the presence of endothelial Ephrin-B2." (PMID 34360793, 2021). "The soluble EphB4-stimulating ligand Ephrin-B2-Fc or the EphB4 RTK inhibitor NVP-BHG 712 were applied during the hematogenous dissemination of metastatic melanoma cells." (PMID 34360793, 2021). "The underlying mechanisms remain elusive and require further analysis to elucidate the cellular consequences of EphB4 inhibition in spinal melanoma metastatic disease." (PMID 34360793, 2021). "Apart from them, overexpression of EphB4 in A375 melanoma cells was accompanied by activation of a multitude of signaling pathways, e.g., the JAK/STAT, Ras/Raf/MEK, and NFkB pathways." (PMID 33153234, 2020). "Nevertheless, overexpression of EphB4 in A375 melanoma cells also influenced expression of 9 angiogenesis-related proteins (Ang-1, VEGF, Akt/PKB, TIMP-1, TIMP-2, TIMP-3, IL-8, TGF-β2, TGF-β R3)." (PMID 33153234, 2020). "In a previous study, EphB4 was demonstrated to be a positive regulator of A375-melanoma growth but a negative regulator of tumor vascularization and perfusion." (PMID 33153234, 2020). "Inhibition of EphB4 by NVP overcomes the acquired resistance to cisplatin in melanoma xenograft models." (PMID 32850441, 2020). "In the human melanoma cell model used overexpression of EphB4 resulted in increased cell proliferation in vitro and tumor growth in vivo." (PMID 29462967, 2018). "In this study, we demonstrate EphB4 to be a promotor of tumor growth and hypoxia and an inhibitor of tumor vascularization and perfusion in A375 melanoma xenografts in vivo." (PMID 29462967, 2018). "Overexpression of EphB4 in A375 melanoma cells slightly but significantly increased both cell proliferation in vitro and tumor growth in vivo." (PMID 29462967, 2018). "In our present study comprising 49 mice we observed an increased tumor growth of EphB4 overexpressing melanoma xenografts, which is in line with the increased proliferation of A375 EphB4 cells in vitro." (PMID 29462967, 2018). "In this regard, EphB4 was shown to promote tumor growth only when melanoma cells co-express EphrinB2." (PMID 29462967, 2018). "Considering the limited in vivo data available, we have conducted a systematic multitracer and multimodal imaging investigation in EphB4-overexpressing and mock-transfected A375 melanoma xenografts." (PMID 29462967, 2018). "Recent experiments depicted reverse signaling, mediated via ephrinB2, to act tumor promoting despite destabilizing tumor vascularization following EphB4 overexpression in malignant melanoma." (PMID 29987450, 2018). "Results revealed EphB4 to be a positive regulator of A375 melanoma growth, but a negative regulator of tumor vascularization." (PMID 29462967, 2018).
melanoma (continued). "EphB4 is highly expressed in most cancer cell types, including prostate, breast, ovarian, colorectal, lung and bladder cancers, melanoma and mesothelioma." (PMID 22194865, 2011). "EphB4-ephrin-B2 bidirectional signaling appears to promote the malignancy of certain cancers, such as melanoma." (PMID 22194865, 2011). "PEGylated TNYL-RAW inhibits EphB4 phosphorylation in melanoma cells stimulated with ephrin-B2 even 24 hours after its addition to cell culture medium, whereas the less stable unmodified TNYL-RAW is ineffective after prolonged incubation in cell culture medium." (PMID 22194865, 2011). "EPHB4 has been shown earlier to promote melanoma cell migration through Rho signaling." (PMID 38426087, 2024). "Consequently, applying NVP-BHG 712 during the metastatic dissemination of melanoma cells inhibits EphB4-mediated forward signaling in tumor cells." (PMID 34360793, 2021). "Similarly, EPHB4 overexpression characterized several tumours such as breast, prostate, colon, uterus, melanoma and ovarian one." (PMID 32336043, 2020). "Moreover, EphB4 overexpression was accompanied by resistance against the DNA-damaging agent cisplatin in an A375 melanoma xenograft model, also used in the present study." (PMID 33153234, 2020). "The present study shows that despite the significantly different inhibitory profiles of NVP and NVPiso, overexpression of EphB4 in A375 melanoma cells had similar effects on tumor characteristics independent of the treatment of the mice with vehicle, NVP, or NVPiso." (PMID 33153234, 2020). "This may, in part, be an explanation for the EphB4-mediated cisplatin resistance of A375 melanoma xenografts." (PMID 29462967, 2018). "Incidentally, the decreased perfusion and vascularization of A375-EphB4 melanoma xenografts may be an explanation for failure of EphB4 targeted imaging approaches by our group." (PMID 29462967, 2018). "Increased expression of EphB4 was confirmed by western blot analysis and quantitative real-time RT-PCR in A375 melanoma cells transfected with pIRES2-AcGFP1-EphB4 (A375-EphB4), but not in A375 cells transfected with mock plasmid (A375-pIRES) or non-transfected control (A375)." (PMID 29462967, 2018). "Since lymph vasculature is an important route for tumor cell metastasis and lymphangiogenesis was the most sensitive prognostic indicator for lymph node metastasis of cutaneous melanoma, we investigated if EphB4 also influences the amount of lymph vessels in the A375 melanoma xenograft model." (PMID 29462967, 2018). "Due to its potential influence on, particularly, tumor vascularization and hypoxia, functional expression of EphB4 should be considered as potential differentiating characteristics or biomarker of malignant melanoma, which preferentially should be determined by non-invasive imaging." (PMID 29462967, 2018). "However, in an A375 melanoma xenograft model EphB4 overexpression has been found to be responsible for resistance to cisplatin, a DNA-damaging compound commonly used in the treatment of malignant melanoma." (PMID 29462967, 2018). "Consistent with increased stability, submicromolar concentrations of PEGylated TNYL-RAW effectively impair EphB4 activation by ephrin-B2 in cultured B16 melanoma cells as well as capillary-like tube formation and capillary sprouting in co-cultures of endothelial and epicardial mesothelial cells." (PMID 22194865, 2011). "A direct role for EphB4 in tumour angiogenesis has been suggested by experiments showing that A375 melanomas form smaller tumours in the presence of soluble EphB4 possibly because the soluble EphB4 interferes with binding of endogenous EphB4 on tumour cells to ephrin-B2 on endothelial cells." (PMID 16171530, 2005). "However, the promigratory effects of EphB4 in A375 melanoma cells are independent of forward signaling, underlining the importance of reverse signaling for migratory processes, which are decisive during metastatic dissemination." (PMID 34360793, 2021).
melanoma (continued). "Therefore, functional expression of EphB4 may represent both a promising biomarker and theranostic target in malignant melanoma." (PMID 29462967, 2018). "In conclusion, functional expression of EphB4 is considered a promising differentiating characteristic, preferentially determined by non-invasive in vivo imaging, which may improve personalized theranostics of malignant melanoma." (PMID 29462967, 2018). "By contrast to CD31 positive blood vasculature, amount of LYVE-1 positive lymph vasculature was not significantly influenced by EphB4 overexpression in the A375 melanoma model, perhaps because of the broad intertumoral variability in lymphatic vessel density." (PMID 29462967, 2018). "We have demonstrated the receptor tyrosine kinase EphB4 to be a positive regulator of tumor growth, but a negative regulator of tumor vascularization in A375 melanoma xenografts in vivo." (PMID 29462967, 2018). "Inhibition of EphB4-ephrin-B2 interaction by PEG-TNYL-RAW could also be useful to inhibit the growth of cancer cells in which EphB4-ephrin-B2 interaction promotes tumorigenesis, such as melanoma cells." (PMID 22194865, 2011).
ovarian carcinoma (16 papers, 2007 to 2026). A malignant neoplasm originating from the surface ovarian epithelium. "EPHB4, in turn, is linked with the proliferation of ovarian carcinoma cells and LIMK2 with actin microfilament disruption in porcine oocytes." (PMID 30338064, 2018). "EPHB4 RTK is expressed in 86% of invasive ovarian cancers and was associated with advanced stage, worse survival, and decreased response to chemotherapy." (PMID 24999452, 2014). "Studies on ovarian carcinoma cells, that endogenously express both EphB4 and EpoR, demonstrated that both ephrin-B2 and Epo directly activate EphB4, causing increased proliferation and invasive migration mediated by Scr kinase (a cytosolic non-receptor tyrosine kinase) and STAT3." (PMID 29393890, 2018). "This work establishes a translational strategy for large-scale eEV production, advancing EV-based delivery platforms for precision targeting of EphB4-expressing ovarian cancer." (PMID 42023984, 2026). "EPHA2, the most extensively studied EPH in ovarian cancer, exhibited overexpression both in ovarian carcinoma cell lines and patient tissue samples, while EPHB4 was found to be upregulated in endometrial cancer in a series of studies." (PMID 35328669, 2022). "It has been reported that EPHB4 overexpression is related to destitute forecast in patients with ovarian cancer." (PMID 34336153, 2021). "Two antibodies against the fibronectin domains in EphB4, mAb47 and mAb131, were found to inhibit tumor growth in a range of EphB4-expressing xenograft models, including prostate, colon, head and neck, and ovarian cancer." (PMID 32397088, 2020). "It has been reported that SRC is activated by EPHB4 in ovarian carcinoma models suggesting the role of SRC kinase in regulation of MYC." (PMID 31641103, 2019). "Correlated expressions of EphB4 and ephrinB3 with strong expression in epithelial ovarian cancer histotypes address the possibility of involvement of paracrine/juxtacrine signalling through tumour progression." (PMID 18231102, 2008). "EphB4 and ephrinB2 expressions in ovarian cancers were studied to analyse EphB4/ephrinB2 functions against clinical backgrounds." (PMID 18231102, 2008). "All the ovarian cancer specimens revealed strong staining for EphB4 and ephrinB2 in the cancer cells and very faint staining in vascular endothelial cells." (PMID 18231102, 2008). "EphB4 expression in human ovarian samples was assessed by immunohistochemical staining of sections isolated from seven normal ovaries and 85 invasive epithelial ovarian cancers." (PMID 17353927, 2007). "To study the biological role of EphB4, we wanted to determine the expression level of EphB4 in ovarian carcinoma cell lines in comparison with benign ovarian tumour cell lines." (PMID 17353927, 2007). "High expression of EphB4 was detected in 69% of high-stage ovarian cancers compared with 19% of low-stage ovarian cancer (P<0.001)." (PMID 17353927, 2007). "EphB4 knockdown effectively reverses these phenomena and inhibits tumour growth in a murine xenograft model of ovarian cancer." (PMID 17353927, 2007). "To determine the biological function of EphB4 in ovarian cancer, we designed several siRNAs to knockdown EphB4 expression and selected the compound that best-inhibited EphB4 expression on Western blots." (PMID 17353927, 2007). "Western blots revealed that EphB4 was indeed expressed highly in ovarian carcinoma cell lines Hey, CAOV-3, Hoc-7, and OVCAR-3, and least in the benign ovarian cell lines MCV-50 and ML-5." (PMID 17353927, 2007). "EphB4 is highly expressed by a majority of ovarian cancers and its expression correlates with advanced disease stage, presence of ascites and decreased survival." (PMID 17353927, 2007). "In this study, we have evaluated the expression of EphB4 in ovarian cancer specimens using highly sensitive and specific monoclonal antibodies against the extracellular domain of EphB4." (PMID 17353927, 2007).